CD38 (CD38 molecule)
Diseases named in the same sentence as CD38 in open-access papers (continued):
Sharing a sentence is not in itself a finding about the gene and the disease.
immune dysfunction (20 papers, 2015 to 2025). "The roles of CD38 in human disease, particularly immune disorders, have been the focus of extensive research for more than four decades." (PMID 39575239, 2024). "In contrast, we did not observe a correlation between the frequencies of HLA-DR+ CD38+ Tc17 cells (that have more persistent dysfunction), and the CD4:CD8 ratio (rho = − 0.01, P = 0.9), associated with immune dysfunction in HIV infection." (PMID 36104716, 2022). "The results obtained suggested that DHL patients suffered immune dysfunction according to the changing of immune cell population, and some of the biomarkers, such as CD38, could be useful in diagnosis of DHL, or even be potential therapeutic agents or targets." (PMID 36823603, 2023). "Saliva α-diversity was associated with CD4/CD8 T cell ratio, a measure of immune dysfunction inversely correlated with morbidity and mortality (Shannon Padj = 0.08; Chao Padj = 0.03) and with activated CD8 T cells (percentage of HLA-DR+ CD38+ CD4 T cells, Chao Padj = 0.02)." (PMID 32024712, 2020). "Furthermore, closer monitoring of immune activation markers like CD38 and HLA-DR in HAART-treated patients could help identify those at risk of immune dysfunction despite viral suppression, guiding personalized therapeutic strategies." (PMID 40333129, 2025). "CD38+ B cells, exhibiting elevated levels of ZAP-70 and heightened protein tyrosine phosphorylation, are associated with increased production of pro-inflammatory cytokines and suppression of CD4+ T cell proliferation, thus contributing to the pathogenesis of immune disorders." (PMID 39044820, 2024). "However, significant differences were detected between IAC patients and non-IAC patients in the training cohort, including immune system disease, BDG positivity, gastrointestinal perforation, CD28+CD8+ T cell-count, DR+CD8+ T cell-count and CD38+CD8+ T cell-count (p< 0.05)." (PMID 39726780, 2024). "Also, in our study we did not evaluate other markers of immune dysfunction that are known to be important in HIV infection, such as immune activation, including increases in HLADR+ CD38+ CD4 and CD8 T cells, and immune exhaustion, characterized by increased expression of the marker PD1 on T cells." (PMID 33828220, 2021).
bacterial infection (19 papers, 2015 to 2025). "On the contrary, accumulated evidence indicates that CD38-knockout (KO) mice are more susceptible to pathogenic bacterial infection and CD38 deficiency can aggravate the inflammatory response." (PMID 33860064, 2021). "For instance, CD38 has been shown to limit bacterial infection, as evidenced by increases susceptibility to Salmonella typhimurium infection in CD38-deficient macrophages." (PMID 33329591, 2020). "As a consequence, CD38-deficient neutrophils are less capable of accumulating at sites of bacterial infection, and CD38-deficient DCs fail to prime Th cells resulting in impaired T cell dependent antibody responses in mice." (PMID 25938500, 2015). "CD38 is closely related to many inflammatory pathways, but its role in liver injury caused by bacterial infection remains unclear." (PMID 33860064, 2021). "In hematological malignancies, the CD38-CD31 axis may promote lymphocyte proliferation, particularly in chronic lymphocytic leukemia.CD38 also contributes to innate immune responses, as CD38-deficient mice display impaired immune responses following bacterial infections." (PMID 40529366, 2025). "Future studies should determine why old murine BMMs express higher CD38 compared to young controls after bacterial infection." (PMID 40649955, 2025). "Although old murine BMMs displayed a delayed immune response to Aa or Pg infection, the old murine BMMs still expressed higher detectable CD38 protein levels at 8 h after bacterial infection compared with the young controls." (PMID 40649955, 2025). "Inhibition of CD38 by 78c dose-dependently reduced CD38 mRNA levels in cells with bacterial infection or AGEs stimulation." (PMID 39682719, 2024). "In the case of CD38, cADPR has been shown to control neutrophil chemotaxis following bacterial infection and CD38-induced cADPR generation augmented the proinflammatory response in response to respiratory syncytial virus." (PMID 38176648, 2024). "Defective CD38 signaling in neutrophils has been shown to result in bacterial infection with impaired innate immunity." (PMID 36499104, 2022). "Both CD38 and HLA-DR are markers of T-cell activation in response to bacterial infection or vaccination." (PMID 31952232, 2020). "In macrophages, CD38 expression is required for the control of bacterial infection mediated by LXR through a mechanism that involves consumption of NAD72." (PMID 29463868, 2018). "Mice lacking CD38 are very susceptible to acute bacterial infections, implicating CD38 in innate immune responses." (PMID 39840045, 2024). "Tightly regulated activity of CD38 is important for homeostasis, since complete absence of its activity, as demonstrated in CD38 knockout mice, causes impairment in insulin secretion, increases susceptibility to bacterial infections and leads to changes in social behavior." (PMID 35457123, 2022). "However, it is possible that CD38 may have a key role in the immune response to bacterial infections." (PMID 31214171, 2019). "Furthermore, the lack of functional CD38 expression or the selective interference with its receptor or enzymatic activities in myeloid cells resulted in reduced production of pro-inflammatory mediators in response to LPS or to bacterial infection." (PMID 36998049, 2023).
hematological cancers (17 papers, 2015 to 2025). "The binding of CD38 antibodies to various hematologic tumor cell lines (Raji, Daudi, L-1236, NCI-H929, Reh, and MOLM-13) in vitro was assessed via flow cytometry." (PMID 38983860, 2024). "We evaluated the ability of anti-CD38 antibodies to kill CD38+ hematologic cancer cell lines through ADCC, CDC, ADCP, and apoptosis induction using in vitro assays and inhibited CD38 enzymatic activity." (PMID 38983860, 2024). "Here, we examine how CD38-mediated mechanisms have been hijacked for tumorigenesis in the various hematological cancers and how these can be potentially exploited to enhance monoclonal antibody-mediated antitumor responses." (PMID 36139103, 2022). "The anti-CD38 antibody therapy, felzartamab, has shown successful depletion of plasma cells in the autoimmune-driven nephropathy MN and hematologic cancers, such as MM." (PMID 35628935, 2022). "In fact, for many aggressive hematological cancers, including CLL, DLBCL, T-ALL, and NKTL, CD38 expression is significantly associated with poorer prognosis and a hyperproliferative or metastatic phenotype." (PMID 36139103, 2022). "High expression of CD38 is consistently found on malignant plasma cells from MM patients, as well as on malignant cells from other hematological cancers such as GCB-DLBCL." (PMID 32922390, 2020). "In conclusion, we show that CD38-specific nanobody-based humanized IgG1 heavy chain antibodies mediate cytotoxicity against CD38-expressing hematological cancer cells in vitro, ex vivo and in vivo." (PMID 32194826, 2020). "We demonstrated the feasibility of using CD38-specific hcAbs to efficiently kill hematological cancer cells in vitro, ex vivo and in vivo." (PMID 32194826, 2020). "Due to increased expression of CD184/CXCR4 and CD38, RPCI-WM1 represents a valuable model in which to study the effects anti-CXCR4 or anti-CD38 targeted therapies that are actively being developed for treatment of hematologic cancers." (PMID 25853860, 2015). "Ongoing trials are evaluating its efficacy in combination with immune checkpoint inhibitors (NCT04381650) and monoclonal antibodies targeting CD38 and CD20 (NCT04776018, NCT04074330) for hematologic cancers." (PMID 40308776, 2025). "Although some CD38 CAR-T cells targeting MM have been reported, clinical treatment with more novel CAR-T cells is needed to advance the treatment of hematological cancers." (PMID 34513682, 2021). "Although CD38 CAR-T cells targeting MM have been reported, there are still no approved CD38 CAR-T cell products for clinical use; thus, more novel CD38 CAR-T cell clinical treatments are needed to advance the treatment of hematological cancers." (PMID 34513682, 2021). "In addition, in this second phase, the LymphoclonalTM tube was replaced by LST, which included both CD45 and CD56 for improved distinction between hematopoietic and non-hematopoietic tumors and, e.g., CD4, CD8, anti-Igκλ, and CD38 for more accurate B, T, and NK cell subsetting." (PMID 34638431, 2021).
metabolic disease (17 papers, 2015 to 2026). A congenital disorder (due to inherited enzyme abnormality) or acquired (due to failure of a metabolically important organ) disorder resulting from an abnormal metabolic process. "For example, the dysfunction of CD38 has been associated with weakened immune responses, metabolic disorders, and behavioral changes in mice." (PMID 38921477, 2024). "Although increased CD38 expression in metabolically abnormal cells has been well documented, further studies are needed to investigate the exact role of CD38 in metabolic diseases." (PMID 40529366, 2025). "Apigenin is a potent inhibitor of CD38, and knockout models have shown resistance to metabolic disorders and exhibit increased NAD+ levels." (PMID 36678315, 2023). "In this review, we summarized the role of CD38 in the pathogenesis of aging and cardio–renal–metabolic diseases, primarily from reports of basic research using animal models." (PMID 36831262, 2023). "Using a combination of biochemical analysis and behavioral testing, we analyzed the effects of the CD38 inhibitor on energy metabolism disorder, the neuroinflammatory response, and the cognition of AD mice." (PMID 35241173, 2022). "Collectively, these results clearly suggest that CD38 inhibition resulted in elevated levels of fatty acid β-oxidation, which is a beneficial energetic shift that could be important in the treatment of metabolic disorders." (PMID 41159029, 2025). "Interestingly, CD38 inhibitors, such as apigenin, have been used as potential drugs for treating metabolic disorders." (PMID 35806906, 2022). "Importantly, cyclic ADP-ribose, NAAD(P), and ADP-ribose serve as significant Ca2+-mobilizing second messengers, indicating CD38′s pivotal role in activating Ca2+ signaling and influencing diverse cellular processes, including immune cell activation and metabolic disorders." (PMID 38921477, 2024). "Moreover, CD38 overexpression in Aβ1-40 injured BV2 cells led to a significant decrease in NAD + and an increase in inflammatory cytokines, suggesting a close relationship between CD38-mediated energy metabolism disorder and neuroinflammation in aging microglia." (PMID 35241173, 2022). "Similar results of CD8+MAIT, CD38+CD8+MAIT cells and reduced expression of IL-17 were observed in PCOS patients with metabolic dysfunction as compared to controls with metabolic disorders." (PMID 34847942, 2021). "Like CD38, SARM1 expression or activity may increase in ageing or metabolic disease and SARM1 could also be involved in pathologies related to NAD+ decline." (PMID 38176648, 2024).
cardiovascular diseases (8 papers, 2021 to 2025). "CD38 is a main NAD+-consuming enzyme in mammals, and our previous results showed that CD38 plays the important roles in many cardiovascular diseases." (PMID 38673941, 2024). "Studies showed that the expressions or activities of most sirtuins in NAFLD were down-regulated 9 and CD38 was a key regulator in cardiovascular disease and metabolic syndrome through NAD+/Sirtuins signaling." (PMID 34803499, 2021). "CD38, a main hydrolase of NAD+ in mammals, plays an important role in various cardiovascular diseases, according to our previous studies." (PMID 37958991, 2023). "In addition, increased expression of CD38 has been observed in endothelial cells and macrophages in response to the SASP factors, possibly leading to the initiation and progression of cardiovascular disease, which is related to aging." (PMID 36831262, 2023).
heart disease (8 papers, 2017 to 2024). "Our results suggest that CD38-Sirt6 pathway not only plays important role in aging-related heart diseases, but is also involved in abnormal immunity in many aging-related diseases." (PMID 36490326, 2022). "It is well known that CD38 contributes to the regulation of metabolism at the physiological level and is involved in the pathogenesis of multiple conditions, including ageing, heart disease and inflammation." (PMID 34142751, 2021). "In the present study, we first demonstrated that CD38 was overexpressed in three types of heart disease with H/I injury and in an H/I-induced cell model." (PMID 32363189, 2020). "Studies have suggested the potential use of CD38 as a therapeutic target in cardiac disease." (PMID 37828989, 2023). "However, whether CD38 is involved in H/I-induced cardiac dysfunction, the main cause of mortality is currently unknown, although declines in cellular NAD levels have emerged as potential key factors in H/I-related heart disease." (PMID 32363189, 2020). "The frequency of CD34+CD38− cells observed in IHD and VHD samples was lower than the frequency reported in bone marrow samples from healthy individuals, showing that the hematopoietic stem cell compartment is also affected in heart disease patients." (PMID 28819363, 2017).
neurodegenerative disease (8 papers, 2020 to 2026). A disorder of the central nervous system characterized by gradual and progressive loss of neural tissue and neurologic function. "Relevant to the hallmarks of neurodegenerative disease, Cd38‐deficient astrocytes also had disruptions to genes that regulate DNA/RNA functions (Trex1), protein homeostasis (Ubb), and cellular bioenergetics (Cox10)." (PMID 41400119, 2026). "Of note, several data tend to indicate that CD38 expression increase in the brain as a consequence of aging, the primary risk factor associated with the vast majority of neurodegenerative diseases, including PD." (PMID 34504106, 2021). "Yet, CD38 expression increases as a consequence of aging which is otherwise the primary risk associated with neurodegenerative diseases, and several experimental data demonstrated that CD38 knockout mice are protected from neurodegenerative and neuroinflammatory insults." (PMID 32085567, 2020). "While CD38 protein abundance often increases with age and in other neurodegenerative diseases such as AD and PD, the significant reduction of this pro-inflammatory protein is consistent with a non-inflammatory-mediated primary pathology in FXTAS." (PMID 33585555, 2020). "It has been reported that CD38 is involved in neurodegenerative diseases; thus, sUA in central nervous system tissues may directly inhibit CD38 activity to limit neuroinflammation and the progression of such diseases." (PMID 39527634, 2024). "Moreover, nicotinamide adenine dinucleotide, whose levels are tightly controlled by CD38, is a recognized and potent neuroprotective agent, and NAD supplementation was found to be beneficial against neurodegenerative diseases." (PMID 32085567, 2020).
kidney diseases (7 papers, 2008 to 2026). "In a word the potential of the CD38 monoclonal antibodies in kidney diseases remains to be exploited." (PMID 38799465, 2024). "Some studies also discusses how blocking CD38 can potentially reduce kidney injury and explores the therapeutic potential of CD38 monoclonal antibodies for kidney diseases like allergic purpura nephritis and granulomatous polyangiitis." (PMID 38799465, 2024). "CD38 monoclonal antibodies offer hope for refractory kidney diseases and an alternative for sensitized kidney transplant candidates." (PMID 38799465, 2024). "This review summarizes the application of CD38 monoclonal antibodies in different kidney diseases and highlights future prospects." (PMID 38799465, 2024). "Due to its ability to increase the number of T cells in the bone marrow and blood, thereby enhancing the immune response against malignant clone cells, anti-CD38 antibodies may also be used for other kidney diseases." (PMID 38799465, 2024). "Conversely, several studies have reported that inhibition of CD38 may lead to the exacerbation of the pathological conditions such as insulin secretion, and cardiovascular and kidney disease." (PMID 36831262, 2023).
inflammation (5 papers, 2016 to 2025). Aberrant reaction of the microcirculation characterized by movement of fluid and leukocytes from the blood into extravascular tissues. "In IBD patients with active intestinal inflammation, the activation of CD25+CD45A+ Treg cells by circulating CD38+effector T cells increased, and the frequency of TIGIT+ cells decreased." (PMID 38202824, 2024).
infectious disease (4 papers, 2018 to 2025). A disorder directly resulting from the presence and activity of a microbial, viral, or parasitic agent in humans. "Our findings may provide a novel insight into the molecular mechanisms underlying CD38-mediated inflammatory response in macrophages, which might play a role in the setting of infectious disease." (PMID 29977153, 2018). "In mammals, CD38 has also been shown to have an important role in the control of different infectious diseases." (PMID 34917087, 2021). "Importantly, recent studies have further expanded the scope of CD38 research into emerging fields such as stem cell biology and infectious diseases." (PMID 40529366, 2025).
neurological diseases (4 papers, 2008 to 2025). "In treatment-refractory antibody-mediated neurological disorders, daratumumab treatment has been associated with reductions in CD38-expressing T cells, NK cells, and serum neurofilament light chain levels, suggesting immunomodulatory effects and attenuation of active axonal injury." (PMID 41221291, 2025). "Increased CD38 enzymatic activity has been implicated in several neurological diseases." (PMID 35712720, 2022). "We initially investigated the expression of Ki-67, HLA-DR and CD38 on CD4+ T cells in PBMC from healthy donors (Control), HTLV-1 infected patients who were clinically asymptomatic (HTLV), or had associated neurological disease (HAM/TSP)." (PMID 18664281, 2008).
blood cancer (3 papers, 2022 to 2025). "This suggests yet again that CD38 surface expression may present as the biggest limiting factor for CD38 therapeutic efficacy in blood cancers with heterogenous expression of CD38." (PMID 36139103, 2022).
peripheral neuropathy (3 papers, 2022 to 2025). A disorder affecting the peripheral nervous system. "The safety profile, and more specifically, the incidence of severe peripheral neuropathy, infections, or IRs was favorable to this combination compared with existing data of anti-CD38-based triplets or quadruplets in the frontline setting in the same patient population." (PMID 37316728, 2023). "Importantly, the addition of anti-CD38 antibodies does not significantly exacerbate the long-term toxicities associated with triplet therapies, such as peripheral neuropathy from bortezomib or cytopenia from lenalidomide." (PMID 40271095, 2025).
psychiatric diseases (3 papers, 2016 to 2021). "Many studies have demonstrated a link between CD38 rs3796863 and OXTR rs53576 polymorphic regions and psychosocial characteristics as well as various psychiatric disorders in adolescents." (PMID 34434131, 2021).
respiratory disease (2 papers, 2018 to 2025). "The findings may provide novel evidence for the prevention and treatment of respiratory disease through CD38 inhibition." (PMID 30619097, 2018).
adenocarcinoma (1 paper, 2020). A common cancer characterized by the presence of malignant glandular cells. "Knockout of CD38 in A549 human adenocarcinoma cells inhibited anchorage-independent cell growth, cell invasion, and xenograft growth in nude mice." (PMID 32092898, 2020).